IL17A (interleukin 17A)
Diseases named in the same sentence as IL17A in open-access papers (continued):
Sharing a sentence is not in itself a finding about the gene and the disease.
autoimmune encephalitis (17 papers, 2009 to 2025). Inflammation of the brain secondary to an immune response triggered by the body itself. "According to recently published research, patients with NMDAR antibody-associated autoimmune encephalitis had increased IL-6, pentraxin-3, CD40L, and IL-17A in their CSF." (PMID 36048783, 2022). "At disease onset, a high CSF IL-17A concentration correlated with a high modified Rankin Scale (p<0.05), a high Clinical Assessment Scale for Autoimmune Encephalitis score (p<0.001) and ICU admission (p<0.01)." (PMID 34054854, 2021). "Here, we generated IL-17A reporter mice and used these mice to examine the expression of IL-17A at rest, after bacterial challenge, and during the development of autoimmune encephalitis." (PMID 22768117, 2012). "In murine GAS-induced autoimmune encephalitis, CNS-infiltrating Th17 cells secreting IL-17A and IFN-γ were required for the disruption of the BBB that allowed for the transit of antibody and microglial activation leading to neuropathological changes in experimental animals." (PMID 36815140, 2022). "Elevated IL-17A levels in the CSF have also been reported in non-NMDA autoimmune encephalitis, suggesting that CSF IL-17A is likely to play an important role in autoimmune encephalitis." (PMID 36569937, 2022).
cardiomyopathy (17 papers, 2012 to 2024). A disease of the heart muscle or myocardium proper. "As additional original findings, our data showed that the IL17A −152 AA and the IL18 −607 AA genotypes are associated with a reduced risk of developing cardiomyopathy in individuals affected by this illness." (PMID 33193300, 2020). "Herein we investigated potential associations between IL1B, IL6, IL17A, or IL18 polymorphism profiles and cardiomyopathy or T. cruzi parasitemia, as well as the impact of HIV infection on cardiopathy." (PMID 33193300, 2020). "We also describe novel associations between specific IL18, IL17A, and IL1B variant profiles and the risk of cardiomyopathy as well as between a specific IL6 polymorphic genotype and the risk of positive T. cruzi parasitemia." (PMID 33193300, 2020). "Original findings included associations between IL17A rs2275913 AA and IL18 s1946518 AA genotypes with decreased risk of developing cardiomyopathy (OR = 0.27, 95% CI 0.07–0.97, P = 0.044; and OR = 0.35, 95% CI 0.14–0.87, P = 0.023, respectively)." (PMID 33193300, 2020). "The results suggest the possible involvement of the polymorphisms of IL17A and IL17F in the susceptibility to chronic Chagas disease and in development and progression of cardiomyopathy." (PMID 28470012, 2017). "In myocardial diseases, IL-17A may play a role in cardiac fibrosis and remodeling, contributing to cardiomyopathy through modulating cardiomyocytes and cardiac fibroblast." (PMID 38587715, 2024). "Facing the biological and clinical scenarios just described, in the current study we investigated potential associations between SNVs linked to IL1B, IL6, IL17A, or IL18 and the risks of positive T. cruzi parasitemia or development/progression of cardiomyopathy." (PMID 33193300, 2020). "Higher frequencies of CD4+ IL-17A+ T-cells, lower levels of IL10 and IL10, and higher levels of IFNγ and TNFα are observed in individuals with more severe cardiomyopathy." (PMID 33193300, 2020).
endometrial cancer (17 papers, 2019 to 2025). Primary or metastatic malignant neoplasm involving the endometrium (mucous membrane that lines the endometrial cavity). "Invasive macrophages induce ERα expression through epigenetic mechanism mediated by IL17A, which makes endometrial cancer cells sensitive to estrogen." (PMID 33363026, 2020). "It has been reported that M2 macrophages infiltrated in the microenvironment of endometrial cancer can enhance the sensitivity of endometrial cancer cells to estrogen by releasing cytokine IL17A and upregulating the expression of ERα through TET1-mediated epigenetics." (PMID 31440472, 2019).
Hashimoto thyroiditis (17 papers, 2014 to 2025). An autoimmune disorder caused by the production of autoantibodies against thyroid tissue. "It is noteworthy that Th17 cells and serum IL-17A levels infiltrating the thyroid gland were significantly increased in Hashimoto's thyroiditis(HT) with higher TGAb compared with controls." (PMID 32477272, 2020). "The reason why IL-17A accumulation behaves differently depending of the concurrence of Hashimoto ́s thyroiditis remains unclear." (PMID 32139737, 2020). "However, the role of IL-22+ and IL-17A+ CD4+ T cells in the pathogenesis of Hashimoto’s thyroiditis (HT) is not fully understood." (PMID 24404171, 2014). "Papillary thyroid cancer with coexisting Hashimoto’s thyroiditis presents elevated MHC class I expression, which may be the result of IL-17A secretion." (PMID 31159823, 2019). "When there was Hashimoto’s thyroiditis concurrent to PTC, a negative correlation between IL-17A concentration and lymph node metastasis was observed." (PMID 32139737, 2020).
infertile (17 papers, 2012 to 2026). "Our study is the first study to enrich lymphocytes from the follicular fluid and analyze the expression of IFN-γ, IL-4, IL17A, and IL10 in lymphocyte subsets of PCOS patients with infertility using flow cytometry." (PMID 30988342, 2019).
leukemia (17 papers, 2013 to 2025). A malignant (clonal) hematologic disorder, involving hematopoietic stem cells and characterized by the presence of primitive or atypical myeloid or lymphoid cells in the bone marrow and the blood. "IL-17A deficiency or anti-IL-17A treatment significantly inhibited leukemia cell proliferation activity and increased the survival rates of B-ALL mice." (PMID 38172124, 2024). "Flow cytometric analysis showed that IL-17A treatment enhanced the homing of leukemia cells to the BM and spleen in recipient mice." (PMID 38172124, 2024). "The spleen weights and leukemia cell infiltration in the BM, spleen, and LNs were decreased in IL-17A-/- recipients." (PMID 38172124, 2024). "The cocultured cells were treated with anti-human IL-17A neutralizing antibodies or human IgG1 (IgG1) for 24 h, and the proliferation and apoptosis activity of the leukemia cells were then evaluated." (PMID 38172124, 2024). "Considering the blocking effects of anti-IL17A neutralizing antibodies, we first performed a homing assay to determine the impact of anti-IL-17A treatment on the homing of leukemia cells." (PMID 38172124, 2024). "We examined the distribution of leukemia cells in the BM and spleen of both WT and IL-17A-/- mice 16 h after transplantation." (PMID 38172124, 2024). "Flow cytometric analysis showed that IL-17A knockout reduced the homing of leukemia cells to the BM and spleen in recipient mice." (PMID 38172124, 2024). "Similar to IL-17A deficiency, anti-IL-17A treatment reduced the number of B220dim CD19+ cells and Ki-67+ leukemia cells in the BM, spleens, LNs, and PB of recipients, leading to a decrease in the death of B-ALL mice." (PMID 38172124, 2024). "Then, we performed homing assays (prior to 18 h) to investigate the effects of IL-17A treatment on the homing of transplanted leukemia cells (GFP-luc-tagged SupB15 cells)." (PMID 38172124, 2024). "We found that anti-IL-17A treatment reduced the homing of leukemia cells to the BM and spleen of recipient mice." (PMID 38172124, 2024). "To investigate which chemokine participates in the migration of Th17 cells to leukemia cells, we detected the effect of IL-17A on the chemokine secretion of leukemia cells." (PMID 38172124, 2024). "It has previously been reported that LL-37 induces apoptosis in Jurkat T leukemia cells, while IL17A either promotes or induces apoptosis in different cell types." (PMID 31260471, 2019). "IL-4 and IL-17A may be involved in ALL progression by promoting the proliferation of leukaemia cells and inhibiting apoptosis, and can also indirectly affect disease progression by modulating the tumor microenvironment." (PMID 41235219, 2025). "Furthermore, the increased presence of Th17 cells in the leukemia niche and the relationship between IL-17A and leukemia progression in vivo requires further investigation." (PMID 38172124, 2024). "We then investigated how IL-17A stimulated the secretion of CXCL16 from leukemia cells." (PMID 38172124, 2024). "In this study, we found that IL-17A promoted but anti-IL-17A monoclonal antibodies (mAbs) treatment reduced leukemia cells’ homing, suggesting that anti-IL-17A mAbs treatment may render leukemia cells more sensitive to standard chemotherapeutic drugs." (PMID 38172124, 2024). "We found that the depletion of CXCL16 with an anti-CXCL16 neutralizing antibody attenuated leukemia progression and decreased the frequency of Th17 cells in the leukemia niche in vivo, suggesting that IL-17A mediates leukemia progression by promoting CXCL16 secretion." (PMID 38172124, 2024). "To determine whether IL-17A secreted by Th17 cells promotes leukemia development, we separately isolated Th17 cells and leukemia cells from Ph+ B-ALL patients and then cocultured the leukemia cells with the Th17 cells." (PMID 38172124, 2024). "In this study, we showed that IL-17A could induce secretion of the chemokine CXCL16 in the leukemia niche by promoting the nuclear translocation and subsequent activity of NF-κB." (PMID 38172124, 2024).
leukemia (continued). "Moreover, we performed homing assays in IL-17A-/- mice to detect the effect of IL-17A knockout on the homing of leukemia cells by using CFSE-labeled leukemia cells isolated from BCR-ABLtTA mice." (PMID 38172124, 2024). "The engraftment results showed that IL-17A treatment promoted Ph+ B-ALL progression, as indicated by the increased infiltration of leukemia cells in the PB, BM, and spleen, ultimately leading to a decreased overall survival rate of leukemia-engrafted mice." (PMID 38172124, 2024). "Here, we found that in the B-ALL microenvironment, IL-17A secreted by Th17 cells promoted the proliferation and survival of B-ALL cells and increased the secretion of the chemokine CXCL16 by leukemia cells." (PMID 38172124, 2024). "Coculture with Th17 cells increased the percentage of the Ki67+ leukemia subpopulation and the survival of Ph+ B-ALL cells, and these changes were abolished by treatment with the anti-IL-17A neutralizing antibody (anti-IL-17A)." (PMID 38172124, 2024). "The cytokine IL-17A, derived from Th17 cells, promotes Ph+ B-ALL progression and increases CXCL16 expression in leukemia cells." (PMID 38172124, 2024). "Jurkat T cells represent a human leukemia T cell line, which was shown to express RORγ and IL-17A previously and was, therefore, chosen as a suitable cell model for investigations of altered ROR-mediated IL-17A production in this study." (PMID 36140177, 2022). "Additionally, tildrakizumab’s anti-IL-23/Th17 effects may have a benefit in ponatinib therapy, as IL-17A activates BCR-ABL signaling, supporting Ph+ leukemia progression." (PMID 40678003, 2025). "In addition, IL-17A-activated Ph+ B-ALL cells secrete the chemokine CXCL16, which in turn promotes Th17 differentiation, attracts Th17 cells and forms a positive feedback loop supporting leukemia progression." (PMID 38172124, 2024). "Here, we show that Th17 cells and IL-17A are highly elevated in Ph+ B-ALL patients, which in turn promote the progression of Ph+ B-ALL by activating BCR-ABL, IL6/JAK/STAT3 and NF-kB signalling pathways and increasing the secretion of the chemokine CXCL16 by leukemia cells." (PMID 38172124, 2024). "Considering that leukemia cells acted mainly as responders but did not release IL-17A, IL-17RA, the receptor for IL-17A, should be a better marker of leukemia cells responding to IL-17A stimulation." (PMID 38172124, 2024).
lymphopenia (17 papers, 2018 to 2026). Reduction in the number of lymphocytes. "Thus, although IL-6 can promote the differentiation of Th17 cells and the secretion of IL-17A and IL-22, low levels of IL-17A and IL-22 are more likely due to lymphopenia." (PMID 34692846, 2021). "The key signal factors IFN-γ (Ifng), IL17a (formally regarded as IL-17), and IL21 were detected by ELISA to assess the influence of activation and lymphopenia of the CD4+ T cells on the inflammatory state." (PMID 40756359, 2025).
neutropenia (17 papers, 2017 to 2026). A decrease in the number of neutrophils found in the blood. "Other markers such as SDF-1, IL-10, and IL-17A are associated with neutropenia and prolonged anemia." (PMID 39253080, 2024). "Reducing the incidence of neutropenia as an adverse event while targeting IL-17A and reducing the risk of infections in patients will be the focus of future studies." (PMID 37920459, 2023). "For biomarkers not included in CAR-HEMATOTOX but confirmed by clinical studies to be altered, perturbations in stromal cell-derived factor (SDF-1) levels may be associated with late-onset neutropenia, and high levels of IL-10 and IL-17A are risk factors." (PMID 39253080, 2024). "Furthermore, IL-17A inhibitors may increase the risk of neutropenia owing to the immunosuppressive properties of these biologics." (PMID 33432451, 2021). "CAR-T–associated CRS is characterized by an increase in cytokines IFN-γ and TNF-α, while neutropenia is characterized by a decrease in IL-17A and G-CSF." (PMID 41165751, 2026). "Mechanistically, a Th1-Th17 imbalance was observed to drive cooccurrence of CRS and neutropenia in an IFN-γ–dependent manner leading to decreased IL-17A and G-CSF, neutrophil production, and neutrophil survival." (PMID 41165751, 2026). "Neutropenia, an adverse event, has been reported in a few clinical trials of drugs targeting IL-17A, summarized in this review." (PMID 37920459, 2023). "Several models of neutropenia have shown IL‐17A‐independent feedback regulation of granulopoiesis, implicating redundancy in granulopoiesis‐stimulating signals." (PMID 31849180, 2020). "The smaller ratio of IFN-γ to IL-17A in low-grade CRS neutropenia compared with high-grade CRS neutropenia may be attributed to the success of CRS intervention strategies." (PMID 41165751, 2026). "A concern regarding administering anti‐IL‐17A and anti‐IL‐23 antibodies could be neutropenia." (PMID 31849180, 2020). "In patients, we observed an increase in the IFN-γ–to–IL-17A ratio in the peripheral blood during high-grade CRS and neutropenia." (PMID 41165751, 2026). "Peripheral blood samples of patients treated with CAR-T show an increase in IFN-γ–to–IL-17A ratio between high-grade CRS neutropenia and no cooccurrence of CRS neutropenia." (PMID 41165751, 2026). "A significant increase in IFN-γ–to–IL-17A ratio was noted between high-grade CRS neutropenia and no cooccurrence (P < 0.0001) as well as low-grade CRS neutropenia (P < 0.0001) groups at peak-postinfusion." (PMID 41165751, 2026).
non-alcoholic steatohepatitis (17 papers, 2019 to 2025). "Furthermore, IL‐17A and Th17 cells have been implicated in the progression of non‐alcoholic steatohepatitis (NASH) to HCC, highlighting their role in tumor angiogenesis and inflammation‐driven carcinogenesis." (PMID 40922413, 2025).
Opportunistic infection (17 papers, 2014 to 2025). An infection that is caused by a pathogen that would generally not be able to cause an infection in a host with a normal immune system. "Within the context of targeting IL-17A or IL-1β in the clinic, one has to keep in mind that altering proinflammatory immune responses harbors the risk of interfering with the control of acute infection and of susceptibility to opportunistic infections." (PMID 24918427, 2014). "This is supported by an absence of rare opportunistic infections and a lack of efficacy by anti-IL-17A and anti-IL-12/23 therapies in the treatment of AD." (PMID 35967329, 2022).
peritonitis (17 papers, 2013 to 2025). Inflammation of the peritoneum (tissue that lines the abdominal wall and covers most of the organs in the abdomen). "On the other hand, during peritonitis episodes IL-17A peritoneal effluents levels may reach a huge increase, showing the involvement of IL-17A in chronic and acute peritoneal damage." (PMID 36982834, 2023). "In murine peritonitis, γδ T lymphocytes are the main source of IL-17A." (PMID 32987705, 2020). "Animals with peritonitis had higher levels of inflammatory proteins such as CCL3, IL17A and IL6 in abdominal fluid and serum compared to sham." (PMID 40102905, 2025). "Curiously, in peritonitis induced by S. aureus delivery and caecal ligation and puncture (CLP) in mice, γδ T lymphocytes, instead of Th17 cells, were found as the main source of IL-17A." (PMID 36982834, 2023). "In the peritonitis model, IL-17A neutralization and CD4+ effector T cell-depletion equally increased the bacterial load in kidneys of mice vaccinated with 4C-Staph/T7-alum, suggesting that Th17 are the main source of IL-17A in these settings." (PMID 26812180, 2016).
postmenopausal osteoporosis (17 papers, 2012 to 2025). Metabolic disorder associated with fractures of the femoral neck, vertebrae, and distal forearm. "Expression of IL17A inhibits the osteogenic differentiation of MSCs, and T cell-derived IL17A is involved in bone loss and postmenopausal osteoporosis." (PMID 33397451, 2021). "Interleukin (IL)-17A is a well-described mediator of bone resorption in inflammatory diseases, and postmenopausal osteoporosis is associated with increased serum levels of IL-17A." (PMID 32231224, 2020). "The effects on bone loss observed with anti-IL-17A therapies in animal models of postmenopausal osteoporosis raised the question of a specific effect of this cytokine on the bone compared to other proinflammatory cytokines such as TNF-alpha or IL-6." (PMID 31485194, 2019). "Therefore, the effect of the IL-17A blocking agent on the bone would be more relevant to study in patients with postmenopausal osteoporosis or in a subgroup of patients with significant bone loss." (PMID 31485194, 2019). "Interestingly, in estrogen deficiency, activated T cells secrete RANKL, TNF-α, and interleukin (IL)-17A, which amplify bone resorption and contribute to postmenopausal osteoporosis." (PMID 33322156, 2020). "In the absence of estrogen, activated T cells secrete IL-17A, RANKL, and TNF, enhancing bone resorption and causing postmenopausal osteoporosis." (PMID 35164658, 2022).
Splenomegaly (17 papers, 2014 to 2026). Abnormal increased size of the spleen. "It alleviated splenomegaly, decreased IL-17A levels, and improved the stability of the microbial community, which are all much superior to single blue light therapy." (PMID 41482938, 2026). "There was also a greater frequency of splenomegaly in IL-17A−/−IL-2Rα−/− mice (8/22) compared to IL-2Rα−/− mice (0/17) and IFN-γ−/−IL-2Rα−/− mice (0/11)." (PMID 25133396, 2014). "We observed a dramatic increase in the expression of several proinflammatory markers such as Il17a, Ifnγ, Tnfα, IL-1β and Ifitm1, and chemokines such as Ccl1, Cxcl10, Ccl22 and Xcl1, in ATMINΔLNBS1ΔL mice displaying splenomegaly, compared to the other genotypes." (PMID 26544571, 2015). "Herein we noted splenomegaly; spleen weight was greater in IL-17A−/−IL-2Rα−/− mice." (PMID 25133396, 2014). "Hyperforin significantly inhibited imiquimod-induced splenomegaly, reduced serum levels of TNF-α and IL-6, and IL-17A in splenocytes and draining lymph nodes." (PMID 34025642, 2021). "We presumed IL17A antagonization cannot modulate IMQ-induced immune cell mobilization, therefore IL17A-dependent protective effect is not reflected by splenomegaly." (PMID 33509093, 2021).
squamous cell carcinoma (17 papers, 2015 to 2025). A carcinoma arising from squamous epithelial cells. "We found that IL-17A was elevated in squamous carcinoma and adenocarcinoma." (PMID 37978543, 2023). "Furthermore, it has been suggested that IL-17A plays a critical role in promoting hyperproliferation in squamous cell carcinomas through the induction of STAT3 and its regulated oncogenic and antiapoptotic gene expression." (PMID 31083515, 2019).